MET (MET proto-oncogene, receptor tyrosine kinase)
Diseases named in the same sentence as MET in open-access papers (continued):
Sharing a sentence is not in itself a finding about the gene and the disease.
tumor (continued). "NSG mice were injected with c-MET-expressing SK-OV-3/luc tumor cells into the flanks, followed by intratumoral injections of c-MET-CAR-T cells or CD19 CAR-T cells." (PMID 40675157, 2025). "Amivantamab is a humanized EGFR-cMET BsAb that has shown a managed safety profile and broad-spectrum anti-tumor efficacy in patients with EGFR exon 20 insertion, EGFR C797S mutation, MET amplification, or resistance to third-generation EGFR TKI Osimertinib." (PMID 40057807, 2025). "Mutations leading to skipping of exon 14 (METΔex14) within the juxtamembrane domain of MET impair receptor degradation and prolong oncogenic signaling, contributing significantly to tumor progression across multiple cancer types." (PMID 40924941, 2025). "Targeted agents are increasingly used in tumor therapy, such as MET inhibitors and anti-angiogenic drugs." (PMID 40176092, 2025). "MET’s role as a mediator of cell motility can be hijacked in an oncogenic context to further promote tumorigenesis by facilitating tumor invasion and metastasis." (PMID 39858062, 2025). "Recently, with the development of targeted therapeutic strategies against c-MET, it has gained renewed attention due to its central role in tumour development." (PMID 40078386, 2025). "Since then, many MET‐activating mutations, located in the kinase domain, have been identified in nonhereditary papillary renal cancers and found to induce constitutive MET activation, leading to cell transformation and tumor growth in experimental models." (PMID 39980226, 2025). "With advancing understanding of the pathogenesis of OS, the MET signalling pathway has emerged as a key focus of research due to its pivotal role in tumour initiation, progression, and metastasis." (PMID 40599602, 2025). "In this space, MDX2001 is a tetraspecific antibody engaging with TROP2 and c-MET on tumor cells and CD3 and CD28 on cytotoxic T cells, improving their activation and proliferation." (PMID 39858054, 2025). "The direct tumor inhibition effect by EGFR/c-MET signaling blockade was presented in xenograft efficacy models of the benchmark molecule amivantamab." (PMID 39995668, 2025). "Immunofluorescence analysis was conducted to assess the effects of TAS-115, alone or in combination with DOXO, on the c-MET/HGF protein expression in heterotypic tumor spheroids." (PMID 41289612, 2025). "Immunofluorescence staining further demonstrated predominant localization of c-MET in tumor epithelia." (PMID 41048570, 2025). "MAbs targeting the MET receptor primarily function by competitively inhibiting the binding of HGF to MET, effectively suppressing downstream signaling and reducing tumour cell proliferation and migration." (PMID 40599602, 2025). "In tumors, probably also in GC, co-activation of Axl and MET has been reported in aggressive subtypes, and dual inhibition has shown superior anti-tumor efficacy compared to monotherapies." (PMID 41011010, 2025). "Another mechanism of resistance is represented by the amplification of the MET proto-oncogene receptor tyrosine kinase (MET), which constitutes a key mechanism by which tumor cells can influence the blockage of the EGFR." (PMID 40002260, 2025). "Remarkably, MET expression exhibited strong positive correlations with the abundance of tumor-infiltrating immune cells, including CD4+ T cells, CD8+ T cells, neutrophils, and macrophages (all P < 0.0001)." (PMID 41233563, 2025). "Our findings revealed that CEA and c-MET remained consistently overexpressed in tumor tissue and were minimally affected by treatment." (PMID 40563608, 2025). "For instance, cancer-associated fibroblasts (CAFs) have been shown to secrete hepatocyte growth factor (HGF), which activates MET signaling in drug-tolerant tumor cells." (PMID 40894234, 2025). "Unfortunately, after a prolonged period of disease control, the tumor progressed again, suggesting acquired resistance to MET inhibitors." (PMID 41268440, 2025).
tumor (continued). "In detail, the inhibition of MET autophosphorylation leads to the disruption of different signaling pathways that are essential for tumor development, including those mediated by PI3K/AKT, RAS/RAF/ERK, and STAT." (PMID 40565798, 2025). "In this case, crizotinib was given for high MET copy number and achieved prolonged remission, but resistance and tumor progression occurred after 18 months." (PMID 41268440, 2025). "Second, while this study primarily focused on the LUCAT1/c-MET axis, tumor drug resistance is generally the result of multifactorial and multi-pathway interactions." (PMID 41145422, 2025). "By activating downstream signaling pathways, c-MET promotes the proliferation and migration of vascular endothelial cells, thereby supporting tumour growth and metastasis." (PMID 40078386, 2025). "The suppression of MET by miR-1 produces G0/G1 cell cycle arrest and inhibits cell migration, showing its dual role in regulating tumor growth and metastasis." (PMID 40429954, 2025). "This suggests that, despite sharing transcriptional signatures with MET Y1003, METΔex14 can confer additional advantage to the tumor beyond decreased MET ubiquitination." (PMID 40924941, 2025). "Other agents, including HQP8361, dictamnine, and the natural compound berberine, have likewise shown promise in countering MET-driven osimertinib resistance by inhibiting MET signaling and inducing tumor cell apoptosis." (PMID 39941826, 2025). "The patient maintained a favorable response for about 18 months, but disease progression was later accompanied by loss of MET amplification on repeat NGS, indicating a molecular shift in the tumor." (PMID 41268440, 2025). "Overexpression of SPRY2 abolishes the inhibitory effect of co-inhibition of FGFR, EGFR, and MET on tumor growth despite reduced ERK and Akt activation, suggesting that additional mechanisms are involved in the tumorigenic potential of SPRY2 in GB." (PMID 41516252, 2025). "Tepotinib monotherapy was also more effective than sorafenib (targeting VFGFR, PDGFR, c-Kit, RET) in treating HCC patients with MET-positive tumours." (PMID 39780187, 2025). "We have previously demonstrated that in NSCLC tumors harboring MET exon 14 mutations, HGF is expressed in about half of the tumor cells." (PMID 39980226, 2025). "Given the important role of c-MET in tumour development, it has been extensively investigated as a prognostic indicator in a variety of cancers." (PMID 40078386, 2025). "Independent studies have reported elevated levels of HGF and MET in human gliomas compared with control brain tissue, with expression levels correlating to tumor grade." (PMID 40924941, 2025). "In vivo experiments further revealed that MET-overexpressing cells formed solid tumours resembling human OS in immunodeficient mice, with tumour growth highly dependent on MET signalling." (PMID 40599602, 2025). "Applying our pre‐clinical findings, we then treated patients with MET mutant tumours with selected MET TKIs." (PMID 40437874, 2025). "Due to prior thoracic irradiation, reirradiation and surgical interventions were deemed not feasible, prompting this systemic combination to maintain MET inhibition while targeting resistant tumor clones." (PMID 40880848, 2025). "Co-mutated tumours were dominated by EGFR-L858R (71%) and frequently harboured high-level MET amplification (57%)." (PMID 41316444, 2025). "In the previous study, we evaluated the expression of MET and matriptase in the primary tumor and bone metastasis of RCC by using immunohistochemistry (IHC)." (PMID 40299443, 2025). "In this study, we identified a positive correlation between tumor‐intrinsic PD‐1 expression and MET activation in PDAC." (PMID 40673866, 2025). "Cabozantinib is a multi-kinase inhibitor that targets MET, VEGFR, RET, and other tumor-associated tyrosine kinases involved in tumor growth and angiogenesis." (PMID 40850949, 2025).
tumor (continued). "Liquid biopsy-based monitoring of circulating tumor DNA (ctDNA) allows serial detection of emergent resistance alterations, such as secondary EGFR or ALK mutations and MET amplification, often before radiographic progression." (PMID 41472727, 2025). "When activated via binding to its ligand hepatocyte growth factor (HGF), the HGF/c-MET signaling pathway plays a critical role in tissue regeneration and tumor mitogenesis, motility, invasiveness, morphogenesis, and angiogenesis." (PMID 39968425, 2025). "TAS-115 is a novel multi-tyrosine kinase inhibitor that exerts its anti-tumor activity primarily through inhibition of c-MET, as well as VEGFR and PDGFR pathways." (PMID 41289612, 2025). "High c-Met protein OE is defined as ≥ 50% of tumor cells with strong (3+) staining as determined by a simultaneously FDA-approved companion diagnostic test, the anti-MET antibody clone SP44 assay (Roche Diagnostics)." (PMID 41254996, 2025). "MET binds hepatocyte growth factor and plays a role in cell motility, stem-like phenotypes, tumor progression, and dysregulation of cytoskeletal regulation of nuclear shape." (PMID 39416100, 2025). "Another c-MET inhibitor, Crizotinib, successfully shrunk tumours, enhanced survival, enhanced systemic and intratumoural bioavailability of gemcitabine and inhibited peritoneal dissemination in murine models of PDAC." (PMID 41561521, 2025). "This fusion gene encodes a chimeric protein that functions as an aberrant transcription factor, promoting tumor angiogenesis and cellular proliferation by activating the MET signalling pathway." (PMID 41378302, 2025). "ERBB2 (HER2) and MET are both well‐established oncogenes that drive tumor growth, survival, and therapy resistance." (PMID 40952239, 2025). "In PDAC, elevated AHNAK2 levels promote tumor progression by preventing c-MET degradation, thereby sustaining HGF/c-MET pathway activation." (PMID 40308776, 2025). "In other malignancies, MYC and MET have been shown to cooperate to drive tumorigenesis, and their co-overexpression tends to exacerbate tumor growth and patient prognosis." (PMID 39858062, 2025). "Structural biology studies elucidate that ZM fusion proteins disrupt autoinhibitory conformations, leading to constitutive activation of the MET kinase domain and driving tumor progression to higher grades." (PMID 40654157, 2025). "MET amplification is a well-established driver of tumor proliferation, invasion, and metastasis, particularly in poorly cohesive gastric carcinomas." (PMID 40860829, 2025). "AKT/MET tumor‐bearing mice were administered sorafenib, curcumin, sorafenib plus curcumin, or vehicle." (PMID 40198582, 2025). "Overall, our results provide evidence of TKI type switching as a way to surmount resistance in patients with MET‐driven tumours and demonstrate the sensitivity of the METG1090A, the METY1230S as well as of other recurrent MET mutations to type II inhibition." (PMID 40437874, 2025). "These TKIs specifically bind to the ATP-binding pocket of MET to inhibit receptor phosphorylation and activation, thereby blocking downstream proliferative signaling and suppressing tumor growth." (PMID 41368576, 2025). "In the domain of immunotherapy, the role of the c-MET signalling pathway in regulating the tumour immune microenvironment has attracted increasing attention." (PMID 40599602, 2025). "Blood samples for pharmacokinetics, MET biomarker and ctDNA analyses, and skin/tumour biopsies for pharmacodynamics, c-MET immunohistochemistry (IHC), MET in situ hybridisation (ISH) and MET DNA-ISH analyses were collected." (PMID 40211189, 2025). "The genomic landscape of Spitz neoplasms includes fusions in genes such as ALK, ROS1, MET, RET, or BRAF and mutations in HRAS genes, which influence both the tumor’s biological behavior and morphological features." (PMID 40870546, 2025). "It shows a range of cancers where MET gene fusions were present, detailing the prevalence of these fusions across different tumor types." (PMID 40361420, 2025).
tumor (continued). "The activation of bypass pathways, including HER2 amplification, MET amplification, and PIK3CA/KRAS mutations, promotes tumor survival and proliferation." (PMID 40733125, 2025). "Studies have demonstrated that sustained activation and upregulation of MET can drive the malignant transformation of osteoblasts into OS cells, thereby promoting tumor initiation and progression." (PMID 40599602, 2025). "Tumor‐intrinsic programmed cell death 1 (PD‐1) has been shown to activate the mesenchymal epithelial transition factor (MET) pathway via its phosphorylation in pancreatic ductal adenocarcinoma (PDAC)." (PMID 40673866, 2025). "Given the central role of c-MET in tumor progression and metastasis, it represents a promising therapeutic target in aggressive cancers such as triple-negative breast cancer (TNBC)." (PMID 41289612, 2025). "In the same study, treating lung CSCs with a bispecific antibody targeting CTLA-4 and c-MET effectively inhibited cell proliferation and migration and reduced tumor volume in vivo." (PMID 41233805, 2025). "The study enrolls patients with post-progression tissue biopsy confirmed via central laboratory MET overexpression and/or MET amplification (IHC: 90% of tumor cells staining at 3+ intensity or FISH: ≥10 copies of the MET gene in tumor cells)." (PMID 40725428, 2025). "The intricate interactions between MET and HGF complicate the tumor microenvironment, establishing MET as a vital target for therapeutic intervention in GBM." (PMID 40332008, 2025). "Initially, c-MET-CAR-T cells effectively killed tumor cells in TNBC and HER2+BC lines in vitro, significantly controlling tumor growth in vivo." (PMID 40281554, 2025). "Considering the critical role of the tumor immune microenvironment in cancer progression, we evaluated the correlation between MET expression and immune infiltration levels in THCA via the TIMER database." (PMID 41233563, 2025). "Cabozantinib is an inhibitor of multiple tyrosine kinase receptors involved in tumor growth and angiogenesis, such as MET, AXL, and VEGF receptors." (PMID 40283927, 2025). "In contrast, the suppression of MET signaling leads to a decrease in cellular proliferation, migration, motility, and angiogenesis, underscoring its vital role in tumor growth." (PMID 40881676, 2025). "Collectively, these studies indicate that MET amplification contributes to tumor immune resistance and progression, with higher MET copy numbers increasing this likelihood." (PMID 40575167, 2025). "BLI is a standard tool in numerous preclinical CAR-M studies, including HER2-targeted, c-MET-targeted, and stroma/tumour dual-targeted quadrivalent CAR-M models." (PMID 40574837, 2025). "Amivantamab is a BsAb targeting EGFR and MET, which can bind to both EGFR and c-MET sites outside of tumor cells and also kill tumor cells through mechanisms such as Fc-mediated antibody-dependent cell-mediated cytotoxicity (ADCC) effect." (PMID 41000392, 2025). "The distribution pattern helps in understanding the role of MET gene fusions in different cancer types and their potential impact on tumor progression and treatment strategies." (PMID 40361420, 2025). "Herein, a significant positive correlation between phosphorylated MET (p‐MET) and tumor‐intrinsic PD‐1 is verified, both of which are independently associated with adverse prognosis." (PMID 40673866, 2025). "It has been reported that abnormal activation of c-MET can prompt normal cells to transform into tumour cells and further enhance the invasiveness, metastatic ability and spread of cancer cells." (PMID 40078386, 2025). "The HGF/c-MET signaling pathway plays a pivotal role in tumorigenesis and disease progression, promoting malignant tumor development through diverse mechanisms, including cell proliferation and migration." (PMID 41233563, 2025). "For that, we used a model of HGF humanised mice (hHGFki) that has a knock‐in of human HGF permitting to activate the human MET at the surface of the injected human tumour cells." (PMID 39374163, 2025).
tumor (continued). "In the CCA microenvironment, scRNA-seq analysis revealed a predominant expression of MET in tumor epithelial cells." (PMID 41048570, 2025). "In this patient, initial NGS detected MET amplification as the main oncogenic driver, making the tumor responsive to crizotinib." (PMID 41268440, 2025). "High MET expression markedly increases the migratory and invasive capabilities of tumour cells, whereas MET silencing effectively reduces cell motility, limits distant metastasis, and improves patient prognosis." (PMID 40599602, 2025). "In vivo studies further demonstrated that PHA-665752 effectively inhibited tumour growth in OS xenograft mouse models, providing compelling experimental evidence for MET signalling as a promising therapeutic target in OS." (PMID 40599602, 2025). "In one study, OC competitively inhibited c-MET kinase phosphorylation, reducing cancer cell proliferation, invasion, and angiogenesis, controlling c-MET-driven tumor progression." (PMID 41470892, 2025). "Combined treatment with MET inhibitors and PD-1 inhibitors can enhance anti-tumor immunity and promote tumor regression." (PMID 40575167, 2025). "By analysing the public cancer database TCGA, we investigated c-MET mRNA expression levels in adjacent and tumour tissues from patients with ESCA." (PMID 40078386, 2025). "Teliso-V targets tumor cells overexpressing c-MET by binding with them and releasing cytotoxic components designed specifically to target them, thereby minimizing off-target toxicity as would be in the case of conventional chemotherapy." (PMID 41189945, 2025). "The overexpression of c-MET has been shown to correlate with pathological stage, tumour grade, muscle invasion and lymph node involvement in bladder cancer." (PMID 40078386, 2025). "Another pro-tumorigenic growth factor produced by CAFs is the hepatocyte growth factor (HGF), which binds to c-MET on tumor cells and activates the downstream MAPK, extracellular signal-related kinase (ERK), and PI3K pathways." (PMID 39858054, 2025). "Aberrant activation of MET signalling promotes tumour cell proliferation, migration, and invasion, thereby making targeted inhibition of this pathway a key focus in cancer therapy research." (PMID 40599602, 2025). "Mechanisms include on-target mutations such as C797S, activation of alternative pathways like MET amplification, histologic transformations, and intricate tumor microenvironment (TME) alterations." (PMID 39941826, 2025). "Increased expression of MET was observed in 29 of 31 (93.5%), and increased phosphorylation of MET was observed in 4 of 31 (12.9%) at the primary tumor." (PMID 40299443, 2025). "Our study demonstrated that CEA, EpCAM, and c-MET are abundantly expressed in rectal cancer tumors, with nCRT exerting minimal impact on their expression in both tumor and adjacent normal tissues." (PMID 40563608, 2025). "We demonstrate a modest yet consistent three- to fivefold increase in MET protein levels in response to many stress stimuli relevant to the adverse tumour microenvironment." (PMID 39774381, 2025). "Resistance mechanisms driven by genetic alterations (such as MET amplification), epigenetic modifications, and tumor microenvironment adaptation greatly reduce therapeutic efficacy." (PMID 41064450, 2025). "In contrast, abnormal activation of the c‐MET pathway in tumour tissues can promote the proliferation and metastasis of tumour cells." (PMID 41190648, 2025). "Inhibiting c-MET diminishes neutrophil infiltration and retards tumor progression, demonstrating that c-MET inhibitors can potentially counteract neutrophil-mediated suppression of T cells, thereby synergizing with ICIs." (PMID 40281554, 2025). "We then translated our pre‐clinical findings and treated patients with MET mutant tumours with selected inhibitors." (PMID 40437874, 2025). "Glesatinib is a type II small-molecule TKI that inhibits MET and SMO, both implicated in tumor progression and survival." (PMID 41041285, 2025).